PHF5A (PHD finger protein 5A)
Diseases named in the same sentence as PHF5A in open-access papers (continued):
Sharing a sentence is not in itself a finding about the gene and the disease.
melanoma (3 papers, 2015 to 2025). A malignant, usually aggressive tumor composed of atypical, neoplastic melanocytes. "In this study, we found that the loss of PHF5A leads to massive splicing defects in different target genes in malignant melanoma." (PMID 39212334, 2025). "We found significant upregulation of CHOP on mRNA level after transfection of siPHF5A for 96 hours, indicating that knockdown of PHF5A causes UPR activation in melanoma cells, potentially further explaining the observed apoptotic cell death." (PMID 39212334, 2025). "Our study identifies a crucial role of PHF5A as driver for melanoma malignancy and the described underlying splicing network provides an interesting basis for the development of new therapeutic targets for this aggressive form of skin cancer." (PMID 39212334, 2025). "For example, treatment with vemurafenib, inhibiting activity of mutated BRAF, leads to a downregulation of PHF5A in melanoma cells." (PMID 39212334, 2025). "Further investigating the apoptotic phenotype after the loss of PHF5A in melanoma cells, our study revealed that the knockdown of PHF5A leads to an activation of the unfolded protein response (UPR) via PERK and ATF6‐signalling pathways with an increased expression of C/EBP Homologous Protein (CHOP)." (PMID 39212334, 2025). "We could show an increased amount of cleaved ATF6 (ATF6‐N) as well as a reduction of full‐length ATF6 on protein level after knockdown of PHF5A, indicating that a loss of PHF5A in melanoma cells activates also this second UPR pathway." (PMID 39212334, 2025). "In summary, understanding the role of PHF5A in the spliceosome gives new insights into post‐transcriptional regulation of melanoma cells." (PMID 39212334, 2025). "In this study, we investigated the role of the splicing factor PHD finger protein 5A (PHF5A) in melanoma." (PMID 39212334, 2025). "To further analyse the effect of a PHF5A knockdown on melanoma cell tumourigenicity, we performed a clonogenic assay." (PMID 39212334, 2025). "To investigate the importance of PHF5A for melanoma development, we performed siPool‐mediated knockdown of PHF5A in the three melanoma cell lines MelHo, MV3 and WM1158, and achieved a significant reduction of PHF5A expression on mRNA and protein level." (PMID 39212334, 2025). "The loss of PHF5A results in an increased rate of apoptosis by triggering Fas‐ and unfolded protein response (UPR)‐mediated apoptosis pathways in melanoma cells." (PMID 39212334, 2025). "This work investigates the role of the splicing factor PHD Finger Protein 5A (PHF5A) in melanoma progression." (PMID 39212334, 2025). "Further research is needed to uncover the precise splicing mechanisms of PHF5A and downstream signalling pathways involved in this new regulatory network and its therapeutic implications for melanoma treatment." (PMID 39212334, 2025). "With this study, we were able to highlight the importance of PHF5A as part of the splicing machinery for malignant melanoma cells to promote disease progression." (PMID 39212334, 2025). "PHF5A is upregulated in melanoma cells, leading to an increased splicing rate, which ensures the tumour typical high proliferation rate and apoptosis resistance." (PMID 39212334, 2025). "To further assess the importance of PHF5A in malignant melanoma, we correlated its expression profile with the survival probability of melanoma patients by applying the TCGA‐derived datasets published by the Protein Atlas Database." (PMID 39212334, 2025). "The staining occurred in all tumour cells, again confirming the high PHF5A expression in melanoma cells." (PMID 39212334, 2025). "We observed exon skipping as well as intron retention events in different genes after a knockdown of PHF5A in malignant melanoma cell lines." (PMID 39212334, 2025). "To confirm these findings, we performed qRT‐PCR and Western Blot analysis, which showed an upregulation of PHF5A expression on mRNA and an even higher expression on protein levels in most melanoma cell lines." (PMID 39212334, 2025).
melanoma (continued). "Our data revealed that an siRNA‐mediated downregulation of PHF5A in different melanoma cell lines leads to massive splicing defects of different tumour‐relevant genes." (PMID 39212334, 2025). "Although the deficient splicing pattern does not occur on a global level, we were able to observe strong effects on the melanoma cells like reduced clonogenicity and viability of melanoma cells after the knockdown of PHF5A." (PMID 39212334, 2025). "Since the knockdown of PHF5A does not affect the viability of these indispensable cells of the human skin but results in apoptosis and increased proliferation of melanoma cells, this makes PHF5A to an interesting therapeutic candidate." (PMID 39212334, 2025). "All these results reflect the essential biological role that PHF5A has in malignant melanoma." (PMID 39212334, 2025). "In this study, we investigated the role of PHD finger protein 5A (PHF5A) in malignant melanoma." (PMID 39212334, 2025). "Supporting these results, a correlation between high PHF5A expression and poor overall survival can also be drawn with data of the Mexpress database (p < 0.001), indicating that PHF5A might contribute to tumourigenesis and maintenance of malignant melanoma." (PMID 39212334, 2025). "Here, we could show that PHF5A is upregulated in malignant melanoma cells compared to normal human epidermal melanocytes (NHEM) and shows high protein expression in patient‐derived material." (PMID 39212334, 2025). "These in vitro data were supported by immunohistochemical staining of PHF5A in patient‐derived human tissue samples of 10 primary melanomas and 10 metastases, which all revealed a high homogeneous expression of PHF5A in the melanoma samples, especially in the cell nuclei." (PMID 39212334, 2025). "This study identifies PHF5A as a putative oncogene in malignant melanoma." (PMID 39212334, 2025). "Additionally, high expression of PHF5A leads to worsened survival prognosis for melanoma patients." (PMID 39212334, 2025). "However, the role of PHF5A regarding development and progression of malignant melanoma remains unknown." (PMID 39212334, 2025). "Fundamentally, each investigated melanoma cell line, especially WM1158, showed an increased apoptosis rate after the RNAi‐mediated knockdown of PHF5A." (PMID 39212334, 2025). "Likewise, knocking down PHF5A was effective at increasing AAV vector transduction in other cell types, including A375 melanoma cells and primary cardiac fibroblasts." (PMID 26244496, 2015). "Therapeutic strategies targeting PHF5A could aim to induce apoptosis of melanoma cells while wound healing‐promoting fibroblasts are not harmed by this strategy." (PMID 39212334, 2025).
endometrial adenocarcinoma (2 papers, 2018 to 2023). "Here, connexin α1gene and PHF5A expression in both rat and human endometrial adenocarcinoma cells were determined and compared to their expression in benign cancer tissues." (PMID 37483794, 2023).
esophageal cancer (2 papers, 2023 to 2024). A primary or metastatic malignant neoplasm involving the esophagus. "In conclusion, we discovered that PHF5A expression was significantly elevated in human esophageal cancer and that correlated with a poor prognosis." (PMID 38429756, 2024). "In this work, we found that PHF5A was highly expressed in esophageal cancer tissues compared to para-carcinoma tissues and that was associated with poor prognosis." (PMID 38429756, 2024). "Subsequently, PHF5A knockdown suppressed the esophageal cancer cell growth and tumor formation." (PMID 38429756, 2024). "Collectively, our study indicated that PHF5A played vital roles in ESCC progression and might become a potential therapeutic target for esophageal cancer treatment." (PMID 38429756, 2024).
pancreatic cancer (2 papers, 2023 to 2024). "In pancreatic cancer stem cells, the interaction of PHF5A with PAF1C and DDX3 led to the overexpression of Nanog and other associated genes responsible for stemness genes regulation." (PMID 37483794, 2023). "Notably, PAF1 contributes to the maintenance of pancreatic cancer stemness via its interaction with PHF5A and DDX3, but not through the typical PAF1 complex, Pol II pause release, or stable β-catenin." (PMID 38182897, 2024).
Skin cutaneous melanoma (2 papers, 2023 to 2025). "For example, GEPIA data confirm that higher PHF5A expression can be detected in skin cutaneous melanoma (SKCM) samples compared to non‐tumour samples." (PMID 39212334, 2025).
acute myeloid leukemia (1 paper, 2023). Acute myeloid leukemia (AML) is a group of neoplasms arising from precursor cells committed to the myeloid cell-line differentiation. "Conversely, a notable decreasing expression of PHF5A was also observed in Acute myeloid leukemia (LAML) tissues." (PMID 37845358, 2023).
brain tumor (1 paper, 2019). "PHF5A facilitates recognition of exons with unusual C-rich 3' splice sites in human brain tumor and is required for cell viability." (PMID 30766880, 2019).
clear cell renal cell carcinoma (1 paper, 2023). "By contrast, clear cell renal cell carcinoma (clear cell RCC) was found a lower PHF5A total protein when compared to normal tissues." (PMID 37845358, 2023).
co-infection (1 paper, 2015). "Since Ad5 infection induced PHF5A and SF3B1 displacement, it is plausible that Ad5 co-infection increases expression from AAV vectors, at least in part, through U2 snRNP inhibition." (PMID 26244496, 2015).
esophageal tumor (1 paper, 2024). "Consistently, in our study, we found that PHF5A was highly expressed in esophageal tumor tissues compared to normal esophageal tissues, which was associated with poor survival." (PMID 38429756, 2024).
Kidney chromophobe (1 paper, 2023). "In the meantime, there was a notable reduction in PHF5A expression in Kidney renal papillary cell carcinoma (KIRP), Kidney chromophobe (KICH) and Thyroid carcinoma (THCA) (p < 0.05)." (PMID 37845358, 2023).
leukaemia (1 paper, 2021). "In previous studies, after SF3B1 and PHF5A knockdown, leukaemia cells became highly sensitive to mitomycin C, suggesting that a combination of splicing modulation with DNA damaging agents could achieve synergistic effects." (PMID 35582381, 2021).
medulloblastoma (1 paper, 2023). A malignant, invasive embryonal neoplasm arising from the cerebellum. "We also verified the activation of TrkA-ABL1 cascade and the hyperphosphorylation of PHF5A at Y36 in the Shh-type medulloblastoma mouse model." (PMID 36759599, 2023). "To further gain insight into the function of PHF5A in medulloblastoma, we first verified that downregulation of ABL1 reduced pY36-PHF5A level in centrosome, and pY36-PHF5A decreased the protein level of CEP250 in Daoy cells." (PMID 36759599, 2023). "All these data demonstrated that PHF5A is hyperphosphorylated at Y36 in medulloblastoma." (PMID 36759599, 2023).
squamous cell carcinoma (1 paper, 2023). A carcinoma arising from squamous epithelial cells. "PHF5A has been described to act as a promising cancer stem cell (CSCs) biomarker/prognosticator predicting the prognosis of cancer stem cells in a patient with oral carcinomas i.e. squamous cell carcinoma." (PMID 37483794, 2023).
tumor (19 papers, 2013 to 2025). "While a huge impact on many tumour‐relevant genes is visible, there are also parts of genes or entire genes, which were spliced correctly after the loss of PHF5A." (PMID 39212334, 2025). "Our analysis indicated that PHF5A expression varied between normal and tumor tissues and was linked to clinical diagnosis and prognosis in various cancers." (PMID 37845358, 2023). "PHF5A overexpression was significantly associated with primary tumour sites (P = 0.0171), T classifications (P = 0.0115), and clinical stages (P = 0.0374) in the HNSCC validation cohort." (PMID 37434235, 2023). "PHF5A upregulation was associated with an increase in tumor size, enhanced lymph node metastasis, and pathogenesis of tumor to advanced-stage malignancy." (PMID 37483794, 2023). "Hyperacetylation of PHF5A is considered to be associated with improved tumor pathogenesis that ultimately increased our attention towards therapeutic prospective keeping in view PHF5A as novel oncotarget for tumor treatment." (PMID 37483794, 2023). "Further experiments demonstrated that PHF5A is implicated in NF-κB signaling and knockdown of PHF5A downregulates the activity of NF-κB pathway to inhibit the tumor progression." (PMID 30766880, 2019). "Consistently, in vivo assay demonstrated that PHF5A deficiency was able to attenuate tumor growth." (PMID 38429756, 2024). "Moreover, consistent with in vitro results, Pladienolide B attenuated the tumor formation effect caused by PHF5A overexpression." (PMID 36609277, 2023). "The findings hinted that high PHF5A expression was predominantly connected with increased risk in different kinds of tumor and PHF5A could be a valuable and potential biomarker with significant implications in prognosis." (PMID 37845358, 2023). "The findings have revealed that PHF5A may function as a diagnostic and prognostic factor for various tumor types." (PMID 37845358, 2023). "Collectively, these findings consistently suggested that PHF5A overexpression might be related to tumor development, and could serve as a new diagnostic and prognostic indicator in LAC." (PMID 29566713, 2018). "Besides, the high expression of PHF5A was significantly associated with tumor infiltration." (PMID 38429756, 2024). "Similarly, by interacting with RNA polymerase associated factor PAF1, increased expression of PHF5A correlates with enhanced proliferation and migration in various tumor cell types, including pancreatic tumor, lung cancer, non-small cell lung cancer, and colorectal cancer." (PMID 38813086, 2024). "An upregulation of splicing factors like PHF5A can increase the number of splicing events, which is beneficial for high proliferative tumours." (PMID 39212334, 2025). "By analyzing the relationship between tumor characteristics and PHF5A expression, we found that tumor infiltration was positively correlated with PHF5A high expression (p < 0.05)." (PMID 38429756, 2024). "We here suggested that PHF5A knockdown was capable of suppressing ESCC cell growth, migration in vitro and tumor growth in vivo by performing further loss-of-function experiments." (PMID 38429756, 2024). "PHF5A was differentially expressed between tumor and corresponding normal tissues and was correlated with prognosis in diverse cancers." (PMID 39030507, 2024). "In order to study the PHF5A roles in tumor formation in vivo, xenograft mice model was employed for observing and recording the tumor growth." (PMID 38429756, 2024). "The underlying mechanisms of PHF5A and VEGFA would require more related studies to unravel the tumor-promoting details." (PMID 38429756, 2024). "In-depth rescue experiments illuminated that the promoting role of PHF5A on tumor progression was dependent on the intact VEGFA expression." (PMID 38429756, 2024). "Then, tumor weight was measured as well as tumor size, indicating significant decline by PHF5A knockdown (p < 0.001)." (PMID 38429756, 2024).
tumor (continued). "PHF5A not only participates in the regulation of tumor pathogenesis nevertheless but its contribution in regulating the growth and self-renewal of stem cells is also stated." (PMID 37483794, 2023). "Our research findings clearly demonstrated the importance of PHF5A in tumor immunity, highlighting the potential of PHF5A as a key candidate for anti-tumor immunotherapy." (PMID 37845358, 2023). "The results confirmed a notable variation in the levels of PHF5A promoter methylation among several types of primary tumor and normal tissues and methylation of the PHF5A promoter played a guiding role in prognosis in some cancers." (PMID 37845358, 2023). "The findings suggested a close relationship of PHF5A expression with immune infiltration of tumor cells, indicating its role in regulating tumor immunity across different types of tumors." (PMID 37845358, 2023). "Abnormal functioning of PHF5A (PHD-finger domain protein 5A) is associated with proliferation, invasion, and metastasis of tumor cells; biologically a malignant characteristic of cells." (PMID 37483794, 2023). "PHF5A participation as a promising oncoprotein inducing epigenetic modification of protein acetylation or hyperacetylation in tumor pathogenesis has been well described hitherto." (PMID 37483794, 2023). "In ACC, PHF5A expression increased when the tumor had distant metastasis, whereas in TGCT, PHF5A expression decreased when the tumor had distant metastasis." (PMID 37845358, 2023). "The current research revealed a notable disparity in PHF5A promoter methylation levels between 15 kinds of tumor and the normal tissues." (PMID 37845358, 2023). "Among these, we noticed a substantial connection between tumor grade and PHF5A expression in 6 cancer types, including CHOL, HNSC, LGG, LIHC, PAAD and UCEC." (PMID 37845358, 2023). "In vivo heterograft tumor monitoring for 24 days, it was found that overexpression of PHF5A significantly promoted the tumor formation of GC cells, which was manifested by increased tumor size (P < 0.05), weight (P < 0.01) and KI67 expression." (PMID 36609277, 2023). "Consistently, Pladienolide B (PHF5A inhibitor) treatment reversed the induction of PHF5A overexpression on the malignant phenotypes and tumor formation of GC cells." (PMID 36609277, 2023). "GSCA platform was utilized to investigate correlation of PHF5A expression with anti-tumor drugs sensitivity in pan-cancer." (PMID 37845358, 2023). "Our findings revealed a notable correlation of PHF5A expression with sensitivity of various anti-tumor drugs." (PMID 37845358, 2023). "So far, there is limited information available regarding the involvement of PHF5A in immune system of tumor patients, and further research on the role of PHF5A in tumor immunity remains an area worth exploring." (PMID 37845358, 2023). "It is important to note that the tumor grade increased correspondingly with the increasing expression of PHF5A." (PMID 37845358, 2023). "PHF5A was highly expressed in tumour cells and tissues and correlated with a worse prognosis of HNSCC." (PMID 37434235, 2023). "Upon analysis of these 6 tumor types, it was evident that the expression of PHF5A corresponded directly with the tumor grade." (PMID 37845358, 2023). "PHF5A inhibition also compromised GSC tumor formation in vivo and inhibited the growth of established GBM patient-derived xenograft tumors." (PMID 32228507, 2020). "When comparing the staining results of tumor tissues with those of their paired nontumor tissues, approximately 95% (57/60) and 89.4% (59/66) of the tumor tissues exhibited increased PHF5A expression (T > N) in LUAD and LUSC, respectively." (PMID 30932358, 2019). "PHF5A was highly upregulated in LAC tissues compared with the ANT counterparts, and closely associated with tumor progression and poor patient prognosis." (PMID 29566713, 2018).